TBC1D28 (TBC1 domain family member 28)
Synonyms: FLJ40244
Tractability: No criterion of Open Targets' tractability assessment is met for any kind of drug.
Gene: Protein-coding gene on chromosome 17 (18,634,247 to 18,644,427, reverse strand). Ensembl gene ENSG00000189375.
Subcellular location (Human Protein Atlas): Vesicles; Nucleoplasm
Genetic constraint (gnomAD): Loss-of-function variants: 19 observed, 26.15 expected, observed/expected ratio (o/e) 0.73, 90% interval 0.51 to 1.07. The upper end of that interval is the gene's LOEUF score, 1.07, which puts it in group 4 of 6, group 1 being the genes least tolerant of losing a copy. Missense variants: 193 observed, 226.94 expected, observed/expected ratio (o/e) 0.85, 90% interval 0.75 to 0.96. Synonymous variants: 62 observed, 84.82 expected, observed/expected ratio (o/e) 0.73, 90% interval 0.6 to 0.9.
Homologues: Paralogues in human: TBC1D26 (87% identical), TBC1D3B (39% identical), TBC1D3F (39% identical), TBC1D3G (39% identical), TBC1D3 (39% identical), TBC1D3C (39% identical), TBC1D3D (39% identical), TBC1D3H (39% identical), TBC1D3I (39% identical), TBC1D3K (39% identical), TBC1D3L (39% identical), TBC1D3E (38% identical), and 33 more.
Diseases named in the same sentence as TBC1D28 in open-access papers:
TBC1D28 is named in the same sentence as 1 disease in open-access papers, as found by Europe PMC text mining. Sharing a sentence is not in itself a finding about the gene and the disease.
TBC1D28 shares sentences with these, for which no sentence is quoted: skin cutaneous melanoma (1 paper).